MTOR (mechanistic target of rapamycin kinase)
Diseases named in the same sentence as MTOR in open-access papers (continued):
Sharing a sentence is not in itself a finding about the gene and the disease.
breast cancer (continued). "In further support of this hypothesis, BRD4 was recently identified as a potential target in tamoxifen-resistant breast cancer, but has not yet been linked to mTOR inhibitors." (PMID 25537515, 2015). "And, accordingly, designing effective combination therapies using ACSL4 and mTOR inhibitors together with agents targeting key molecular elements involved in breast cancer relies heavily on the identification of predictive markers that may provide the basis for patient therapy." (PMID 26536660, 2015). "It has been proposed that Akt/mammalian target of rapamycin (mTOR) pathway inhibition may sensitize breast cancer cells to doxorubicin; however, few clinical studies have investigated the association between pAkt expression and the resistance to doxorubicin in breast cancer patients." (PMID 25789027, 2015). "Although the relevance of this pathway has been well documented in the setting of invasive breast cancer and metastasis, our findings suggest that Akt-mTOR signaling may also play a role in the setting of initiation and progression towards breast cancer in ‘normal-like’ breast cells." (PMID 24811059, 2014). "Upregulation of PI3K/Akt/mTOR signalling in endocrine-resistant breast cancer (BC) has identified mTOR as an attractive target alongside anti-hormones to control resistance." (PMID 24457069, 2014). "Furthermore, our model of primary breast cancer can be used as a tool to study the effectiveness of novel mono-therapies and combination therapies that are directed towards cancer that are hyperactive for mTOR and aberrant cancer metabolism." (PMID 25436981, 2014). "Next, we co-transfected miR-99a mimics and mTOR cDNA plasmid that lacks the 3′-UTR into breast cancer cells to determine whether the ectopic expression of mTOR could reverse the inhibitory effect of miR-99a on breast cancer cells." (PMID 24637915, 2014). "miR-99a/mTOR might therefore be used as potential therapeutic targets in breast cancer." (PMID 24637915, 2014). "The mammalian target of rapamycin (mTOR), another protein with key functions in cell growth and proliferation, for example, is able to regulate p73, and treatment with rapamycin sensitizes highly aggressive breast cancer cells to cisplatin through upregulation of TAp73." (PMID 25071017, 2014). "Thus it prompted us to speculate whether GSK3β inactivation was required for Aur-A to activate mTOR signaling in breast cancer." (PMID 25115395, 2014). "Also consistent is that protein levels of the mTOR pathway suppressors, PTEN and INPP4B, are relatively low in BLBC or TNBC patient tumors compared with other breast cancer subtypes; and mTOR pathway-related proteins, especially AKT and 4EBP1, show high phosphorylation levels in BLBCs." (PMID 24708766, 2014). "Proof-of-principal for the value of osteoblast stimulation in the treatment of osteolytic breast cancer metastases was suggested by exploratory studies of bone parameters (reviewed in the BOLERO-2 (Breast cancer trials of Oral Everolimus-2) trial (exemestane + the mTOR inhibitor everolimus)." (PMID 25757219, 2014). "The outcome of our study suggests that the loss of LKB1 expression in HER2 positive breast cancer may serve as a marker for hyperactivation of mTOR, warranting further investigation into combinatorial therapeutics that target LKB1-AMPK-mTOR and glycolytic pathways." (PMID 23451056, 2013). "Interestingly, previous studies on sensitivity of the panel of breast cancer cell lines to mTOR inhibitor, CCI-779, revealed that cells sensitive to CCI-779 were estrogen receptor positive, overexpressed ErbB2 and/or had lost the tumor suppressor gene product PTEN." (PMID 23389114, 2013). "Everolimus is an inhibitor of the mammalian target of rapamycin (mTOR) and has been approved for the prevention of organ transplant rejection as well as for the treatment of subependymal giant cell astrocytoma, neuroendocrine tumors, renal cell carcinoma and breast cancer." (PMID 23822543, 2013).
breast cancer (continued). "In addition, PgR may in the long run be downregulated through PI3K/AKT/mTOR pathway stimulation and subsequent aberrant ER signalling, leading to acquired endocrine resistance among patients with initially ER/PgR-positive breast cancers." (PMID 24131622, 2013). "Since mammary tumors from STK11−/−/NIC mice are positive for elevated ErbB2 expression, and 31% of HER2 positive breast cancers show loss of LKB1 expression, we investigated the effect of a next generation small molecule that targets the EGFR (ErbB1) and HER2, BIBW2992 (BIBW), on mTOR signaling." (PMID 23451056, 2013). "We have previously reported that obese ovariectomized mice implanted with syngeneic mouse mammary tumor cells displayed enhanced mammary tumor development and progression, and this was associated with elevated levels of bioavailable IGF-1 and downstream PI3K/Akt/mTOR signaling." (PMID 23880059, 2013). "We have previously shown that mammary tumors developed in MMTV-Aurora-A transgenic contain phosphorylated U. Since our results indicate that Akt/mTOR is phosphorylated in drug-resistant clones, we hypothesized that activation of Akt/mTOR is involved in anti-apoptotic phenotypes of these cells." (PMID 23383195, 2013). "Furthermore, these findings may be relevant to recent clinicalstudies showing promising benefits from the inhibition of the mTOR pathway in tumorsof breast cancer patients treated with hormonal therapy." (PMID 23874830, 2013). "Thus, the differential expression of mTOR pathway proteins (PTEN and active forms of AKT and S6) may be possibly predictive markers for tumour response to mTOR inhibition, as described in glioblastoma, prostate and breast cancer cell lines." (PMID 22408430, 2012). "This review will focus on the mammalian Target of Rapamycin (mTOR) pathway and also provide a perspective on translational research, from the chemical and pharmacologic characterization of rapamycin to the molecular mechanisms of breast cancer, ending with clinical applications and treatments." (PMID 23369283, 2012). "Thus, the study suggests that blocking of OPN-induced ICAM-1 expression through mTOR/p70S6 kinase signaling may be an important therapeutic target for the management of breast cancer." (PMID 20459645, 2010). "Thus, blocking OPN-induced ICAM-1 expression through mTOR and p70S6 kinase pathway may act as important target for the control of breast cancer." (PMID 20459645, 2010). "The lack of effectiveness of rapamycin in preventing IGFIR acinar phenotype may have important implications on the usefulness of mTOR as a target for breast cancer therapeutics and suggests that rapamycin analogues may be best used in combination with other therapeutics." (PMID 16584539, 2006). "This signal integration function of GNB2 is supported by prior studies in breast cancer, where it was shown to be a direct target of miR-142-3p; GNB2 knockdown activated AKT/mTOR signaling, altered autophagic flux, and modulated chemotherapeutic sensitivity." (PMID 41550840, 2026). "The inhibition of proliferative cascades such as the PI3K/Akt/mTOR and MAPK pathways has been observed in selenium-treated breast cancer cells." (PMID 41496977, 2026). "In breast cancer, MRPL13 promotes cell proliferation, migration, and epithelial-mesenchymal transition via the PI3K/AKT/mTOR pathway, contributing to metastasis and recurrence." (PMID 40841355, 2025). "ENO1 subsequently promotes breast cancer progression by stabilizing the expression of the downstream transcription factor B-MYB, which ultimately activates the PDK1/AKT/mTOR signaling pathway thereby promoting breast cancer progression." (PMID 40303285, 2025).
breast cancer (continued). "This methodology has been effective in uncovering optimal drug targets in various contexts, including previously established targets for breast cancer (e.g., SRC, MTOR) and spinal cord injury (e.g., TNF, FOS, IL6)." (PMID 40895536, 2025). "PROCR is known to activate several signaling pathways in breast cancer cells, including ERK, PI3K–Akt–mTOR, and RhoA–ROCK–p38 pathways." (PMID 40631077, 2025). "In HER2-overexpressing breast cancer, the PI3K/Akt/mTOR pathway has also been connected to trastuzumab resistance." (PMID 40176859, 2025). "The ethyl acetate extract of V. amygdalina leaves exhibited anticancer activity against 4T1 breast cancer cells by inducing apoptosis, enhancing cell accumulation in the G2/M phases of the cell cycle, and inhibiting the expression of PI3K and mTOR." (PMID 40136435, 2025). "In breast cancer cells, TPI is highly upregulated and activates the PI3K/Akt/mTOR pathway to promote tumor progression." (PMID 40612109, 2025). "First, PI3K/AKT/mTOR signaling and PTEN signaling pathways are identified as being involved in breast cancer development." (PMID 39888956, 2025). "Metformin, an insulin-sensitizing biguanide, has demonstrated antiproliferative and pro-apoptotic effects in preclinical breast cancer models via AMPK activation and mTOR inhibition." (PMID 41300964, 2025). "Key signaling pathways affected by miR‐21 include EMT, androgen receptor (AR) signaling, estrogen receptor (ER) signaling, RAS/MAPK, RTK, and mTOR/TSC pathways, all of which are vital in breast cancer progression." (PMID 40567015, 2025). "Empagliflozin exerts anti-proliferative and anti-survival effects by inhibiting mTOR, Akt, and PGC-1α, and it exhibits synergy with tamoxifen in MCF-7 breast cancer cells." (PMID 39066911, 2025). "In letrozole-resistant breast cancer cells, HIF-1α expression remains constitutively elevated through the HER2–PI3K/Akt/mTOR pathway, driving downstream targets such as BCRP that sustain resistance phenotypes." (PMID 41303593, 2025). "Wu365 found that inhibiting endogenous H2S can reduce the vitality, proliferation, migration, and invasion rate of human breast cancer cells, induce apoptosis in human breast cancer cells, and decrease the phosphorylation levels of PI3K, Akt, and mTOR." (PMID 40442106, 2025). "Another study showed that the STAT3 pathway is positively regulated by mTOR signaling, while PTEN functions as a negative regulator of both STAT3 and mTOR pathways in breast cancer." (PMID 41287778, 2025). "Its anticancer effect has been observed in a wide range of cancers, including breast cancer, lung cancer, and pancreatic cancer, involving a number of signaling pathways, such as MAPK, PI3K/AKT/mTOR, NF-κB, and Wnt/β-Catenin." (PMID 40281695, 2025). "Research indicates that in breast cancer, B7H3 expression impedes the proliferation of CD4+ and CD8+ T cells by diminishing the phosphorylation of the mammalian target of rapamycin (mTOR), thereby curtailing the release of IFN-γ." (PMID 39735676, 2025). "We show that R-RAS2 regulates CD98/LAT1 transporter-mediated mTOR pathway activation and mediates CD44-dependent cancer cell migration and invasion, thus providing a mechanism by which R-RAS2 promotes breast cancer cell metastasis." (PMID 40221767, 2025). "Novel approaches, including CDK4/6 and PI3K/mTOR inhibitors, offer combinatorial benefits in HR+/HER2– breast cancer, yet resistance mechanisms necessitate further exploration of alternative signaling cascades and immune-modulating strategies." (PMID 40299687, 2025). "HER2-positive breast cancer resistant cells and tissues showed activation of fatty acid metabolic pathway and PI3K/AKT/mTOR signaling pathway." (PMID 40303293, 2025). "recently reported that HINT3 inhibits the activation of the PTEN/AKT/mTOR signaling pathway, suppressing the proliferation, growth, migration, and tumor development of MCF‐7 and MDA‐MB‐231 breast cancer cells." (PMID 40755357, 2025).
breast cancer (continued). "In CDK4/6 inhibitor-resistant breast cancer cells, tumor growth shifts dependency from hormone receptor (HR) signaling to hyperactivated PI3K/AKT/mTOR cascades." (PMID 40421216, 2025). "HER2 overexpression, found in 15–30 % of human breast cancers, and estrogen receptor-α, positive in 70 % of breast cancers, also increase HIF-α levels via increased PI3K/Akt/mTOR signaling." (PMID 40791817, 2025). "Soy isoflavones exhibit potent anticancer properties in breast cancer by specifically targeting estrogen receptor (ER) and PI3K/Akt/mTOR signaling pathways." (PMID 40612872, 2025). "Newly approved drugs targeting the AKT/mTOR pathway in ER+, HR+, and HER2- breast cancers include Gedatolisib, MK-2206, Capivasertib, Sirolimus, Temsirolimus, Sapanisertib, and Vistusertib." (PMID 41157256, 2025). "Combined inhibition of mTOR and CDK4/6 has been positively evaluated in patients with advanced breast cancer showing acceptable safety profiles." (PMID 40260297, 2025). "In ER + breast cancer, the interaction between the PI3K-Akt-mTOR and estrogen receptor α pathways drives resistance to endocrine therapy." (PMID 39066911, 2025). "In both breast cancer cell lines, we analyzed samples treated with DMSO (mock) or Torin 1, a potent mTOR inhibitor." (PMID 41218079, 2025). "Furthermore, combination of multi-node PI3K/AKT/mTOR inhibition with paclitaxel – even at paclitaxel doses with relatively modest monotherapy efficacy – produced profound tumour growth inhibition and tumour regression in preclinical models of endometrial and breast cancer." (PMID 40360883, 2025). "Using models of endometrial and breast cancer, we evaluated the efficacy of a multi-node PI3K/AKT/mTOR pathway inhibitor approach utilising the dual mTORC1/mTORC2 inhibitor sapanisertib, PI3Kα inhibitor serabelisib and an insulin-supressing diet." (PMID 40360883, 2025). "For example, the activation of HER2 receptors triggers the signalling pathways of PI3K/Akt/mTOR and MAPK, which play a role in the development of breast cancer." (PMID 40417193, 2025). "The oncogenic lncRNA HOTAIR inhibits autophagy in breast cancer via chromatin remodeling and activation of the PI3K/AKT/mTOR pathway." (PMID 41329030, 2025). "Multi-node PI3K/AKT/mTOR pathway inhibition with serabelisib, sapanisertib and ISD is highly effective in preclinical models of endometrial and breast cancer, supporting continued clinical development in these and other solid tumours." (PMID 40360883, 2025). "One example is the activation of the PI3K/Akt/mammalian target of rapamycin (mTOR)-mediated HIF-1α pathway, as seen in many solid tumors, including colon cancer, prostate cancer, and breast cancer." (PMID 41585262, 2025). "Our previous work demonstrated that NQO1 can bind to pyruvate kinase L/R (PKLR), a key regulator of glycolytic reprogramming in breast cancer, thereby activating the AMPK and AKT/mTOR signaling pathways and inducing glycolytic reprogramming." (PMID 39939940, 2025). "Mechanistically, M2 enhances tumor survival via pathways like CCL2/PI3K/Akt/mTOR in breast cancer, IL-6/STAT3 in colon and pancreatic cancers, and CHI3L1 in gastric/breast cancers." (PMID 40940877, 2025). "Gedatolisib, a pan-PI3K/mTOR inhibitor, was evaluated as first-line therapy, combined with standard-of-care palbociclib and letrozole, for patients with HR+/HER2− advanced breast cancer." (PMID 40711480, 2025). "In line to a possible involvement of mTOR in the inhibition of C. parvum infection, an oleocanthal-driven reduction in mTOR phosphorylation by more than 50% was demonstrated in MDA-MB-231 breast cancer cells treated for 72 h with 10 μM oleocanthal." (PMID 41156614, 2025). "In estrogen receptor (ER)-positive breast cancer cells, HK2 suppresses mTOR activity through an interaction with mTOR, which promotes autophagy and chemoresistance to tamoxifen." (PMID 40612109, 2025).
breast cancer (continued). "In breast cancer, the PI3K/AKT/mTOR signaling pathway is a critical signaling cascade that is highly susceptible to hyperactivation." (PMID 40949144, 2025). "PIK3CA exerts clinical effects on patients with breast cancer, particularly through the PI3K/AKT/mTOR pathway." (PMID 40142329, 2025). "In recent breast cancer studies, Ursolic acid (UA) was found to enable transcription factor EB (TFEB) nuclear entry in a partial mammalian target of rapamycin (mTOR)-dependent manner and prevent its ubiquitination." (PMID 40723842, 2025). "PI3K/AKT/mTOR pathway-targeted medicines are presently employed as second-line therapy for HR+ MBC, primarily in patients with breast cancer who have had prior CDK4/6is progress." (PMID 40134916, 2025). "MA downregulated the phosphorylation of AKT and mTOR by decreasing the expression level of RIP1, the key upstream regulator of mTOR/AKT, in breast cancer cells." (PMID 39863145, 2025). "This research investigates the effects of nano-curcumin on the expression of Cyclin D1 and DILA1 genes, as well as on the PI3K/AKT/mTOR pathway, in tamoxifen-sensitive and resistant MCF-7 breast cancer cell lines." (PMID 41348684, 2025). "HK2 has been shown to interact with mTOR and inhibit its activity in TAMR-MCF-7 breast cancer cells." (PMID 40303296, 2025). "There are clinical trials in breast cancer testing hormone therapy combined with CDK4/6 inhibitors and mTOR inhibitors (ex." (PMID 40282469, 2025). "Similar EMT activation has been observed in HER2-amplified breast cancer cells treated with lapatinib, basal-like breast cancer cells exposed to PI3K/mTOR inhibitors, and paclitaxel-resistant lung or prostate cancer cells tolerating EGFR-TKIs58–60." (PMID 40738896, 2025). "In breast cancer CSC models, HIF-2α upregulates CD44 expression via the PI3K/AKT/mTOR pathway, significantly enhancing CSC survival and radioresistance." (PMID 40725100, 2025). "Among the key mechanisms contributing to drug resistance against CDK4/6iin HR‐positive/HER2‐negative breast cancer cells, upregulation of the PI3K/mTOR pathway is particularly common, making it a promising target for overcoming resistance." (PMID 40206206, 2025). "In patients with HR/HER2-advanced breast cancer after progression on the CDK4/6 inhibitor, the patients who applied endocrine therapy in combination with the mTOR inhibitor had a median PFS benefit of 5.1 months." (PMID 39917165, 2025). "Everolimus, an mTOR inhibitor, is FDA-approved for use in both pancreatic NENs and HR-positive breast cancer in combination with exemestane." (PMID 40909459, 2025). "Alterations in the PI3K/mTOR signaling pathway are often seen in triple-negative breast cancers (TNBC), a breast cancer subtype characterized by limited molecularly targeted treatment options and poorer patient outcomes." (PMID 40019775, 2025). "Mechanistically, they selectively target pathways dysregulated in breast cancer, such as PI3K/AKT/mTOR and STAT3, while sparing normal cells, a critical advantage over conventional chemotherapies." (PMID 40136435, 2025). "There are many different ER-targeted drugs and emerging treatments that target peripheral or interconnected pathways in ER+ breast cancers (such as PIK3, mTOR and AKT)." (PMID 40265613, 2025). "In Ehrlich-induced breast cancer in mice, ascorbate (4 g/kg/day, IP) treatment for 15 days exerted anti-neoplastic activity through inhibition of the PI3K/AKT/mTOR pathway." (PMID 39990670, 2025). "It has been found that pomolic acid inhibits the phosphorylation of mTOR and subsequent proteins, such as p70S6K and 4E‐BP1, in cells of breast carcinoma, which is triggered by EGF." (PMID 40717210, 2025).